SIGLEC6 (sialic acid binding Ig like lectin 6)
Description:
Putative adhesion molecule that mediates sialic-acid dependent binding to cells. Binds to alpha-2,6-linked sialic acid. The sialic acid recognition site may be masked by cis interactions with sialic acids on the same cell surface.
Synonyms: Siglec-6; OB-BP1; CD327; CD33L; CD33L1; OBBP1; CD33L2; CDW327
Tractability: Antibody: its Gene Ontology location is reachable by antibodies, with high confidence; UniProt places it where antibodies can reach, with medium confidence; UniProt predicts a signal peptide or a membrane-spanning region; the Human Protein Atlas places it where antibodies can reach.
Gene: Protein-coding gene on chromosome 19 (51,517,819 to 51,531,856, reverse strand). Ensembl gene ENSG00000105492.
Subcellular location: Cell membrane (Isoform 1); Secreted (Isoform 2)
Subcellular location (Human Protein Atlas): Cytosol; Plasma membrane; Predicted to be secreted
Pathways (Reactome):
Immune System: Immunoregulatory interactions between a Lymphoid and a non-Lymphoid cell
Gene Ontology:
Molecular function: protein binding; sialic acid binding
Biological process: cell adhesion; cell-cell signaling
Cellular component: membrane; plasma membrane; extracellular region
Genetic constraint (gnomAD): Loss-of-function variants: 32 observed, 43.87 expected, observed/expected ratio (o/e) 0.73, 90% interval 0.55 to 0.98. The upper end of that interval is the gene's LOEUF score, 0.98, which puts it in group 4 of 6, group 1 being the genes least tolerant of losing a copy. Missense variants: 555 observed, 577 expected, observed/expected ratio (o/e) 0.96, 90% interval 0.9 to 1.03. Synonymous variants: 217 observed, 239.72 expected, observed/expected ratio (o/e) 0.91, 90% interval 0.81 to 1.01.
Homologues: Orthologues: chimpanzee SIGLEC6 (98% identical), macaque SIGLEC6 (84% identical), tropical clawed frog siglecl2 (24% identical), tropical clawed frog siglecl2 (23% identical), tropical clawed frog siglecl1 (22% identical), tropical clawed frog siglecl1 (17% identical). Paralogues in human: SIGLEC5 (52% identical), SIGLEC8 (51% identical), SIGLEC7 (50% identical), SIGLEC9 (50% identical), SIGLEC12 (49% identical), CD33 (45% identical), SIGLEC10 (41% identical), SIGLEC14 (40% identical), SIGLEC11 (38% identical), SIGLEC1 (24% identical), MAG (20% identical), CD22 (17% identical), and 4 more.
Diseases named in the same sentence as SIGLEC6 in open-access papers:
SIGLEC6 is named in the same sentence as 18 diseases in open-access papers, as found by Europe PMC text mining. Sharing a sentence is not in itself a finding about the gene and the disease. The quoted sentences say what the papers report.
preeclampsia (7 papers, 2012 to 2025). Preeclampsia is a hypertensive disorder of pregnancy that is characterized by new-onset hypertension with proteinuria presenting after 20 weeks of gestation, and depending on mild or severe forms may initially present with severe headache, visual disturbances, and hyperreflexia. "Analyses suggested that decreased levels of circulating proteins encoded by SERPINE2 and SIGLEC6 were causal for increased risk of preeclampsia." (PMID 40991151, 2025). "We also identified two circulating proteins (encoded by SERPINE2 and SIGLEC6) as potentially causal for preeclampsia." (PMID 40991151, 2025). "Decreased levels of SERPINE2 and SIGLEC6 were potentially causal for increased risk of preeclampsia." (PMID 40991151, 2025). "Functional enrichment analysis of the 447 human-upregulated DEGs, including ADAM12, ERVW-1, KISS1, LGALS13, PAPPA2, PGF, and SIGLEC6, revealed over-representation of genes implicated in preeclampsia and other pregnancy disorders." (PMID 34154587, 2021). "Interestingly, our pQTL results are consistent with a causal relationship, however, our results imply the opposite direction of effect (i.e. increased serum levels of SIGLEC6 are associated with decreased risk of preeclampsia)." (PMID 40991151, 2025). "From the heatmap, it can be observed that the expression of ANKRD37, CRH, LEP, and SIGLEC6 in preeclampsia placenta is significantly increased." (PMID 38894741, 2024). "Employing weighted gene co-expression network analysis (WGCNA) and lasso regression, four potential target genes (ANKRD37, CRH, LEP, SIGLEC6) are identified for potential prediction of preeclampsia." (PMID 38894741, 2024). "In comparison with the normal control group, the expression levels of the candidate genes ANKRD37, CRH, LEP, and SIGLEC6 in preeclampsia placenta were significantly increased, as visualized by the boxplot function." (PMID 38894741, 2024). "Overall, these findings position SIGLEC6 as a putative regulator of immune and trophoblastic functions relevant to preeclampsia pathogenesis." (PMID 38099221, 2023). "Additionally, increased SIGLEC6 in trophoblast cells impairs vascular endothelial cell function by down-regulating Wnt6/β-catenin signal transduction in preeclampsia." (PMID 38894741, 2024). "Preeclampsia placentas exhibited significantly elevated levels of NKRD37, CRH, LEP, and SIGLEC6 expression compared to the control group." (PMID 38894741, 2024). "In order to further understand the role of screened biomarkers in the diagnosis and prediction of preeclampsia, we based on the nomogram model of four key genes: ANKRD37, CRH, LEP, and SIGLEC6." (PMID 38894741, 2024). "The distinct expression pattern of SIGLEC6 in the human placenta, coupled with its known roles in regulating immune cell interactions and invasion processes, suggests that it may contribute to the aberrant immune activation and shallow trophoblast invasion characteristic of preeclampsia." (PMID 38099221, 2023). "Interestingly, in spite of varied sampling sites or early/late onset of preeclampsia, increased gene expression of SIGLEC6 is repeatedly observed in microarray gene profiling studies in preeclamptic placenta, implying deregulated SIGLEC6 may be tightly associated with pathogenesis of preeclampsia." (PMID 22929622, 2012). "In accordance with the altered trophoblast pathophysiology in early-onset preeclampsia, many of the most differentially regulated genes in women with preeclampsia (LEP, CGB, LHB, INHA, SIGLEC6, PAPPA2, and FLT1) have predominant or unique expression in the syncytiotrophoblasts." (PMID 24991435, 2014). "Notably, several HPGs associated with invasive EVTs (ADAM12, PAPPA2, PGF), and pregnancy complications such as preterm birth and preeclampsia (ADAM12, HSD17B1, KISS1, LGALS13, PAPPA2, SIGLEC6, ERVW-1), were found to be upregulated in human compared to rhesus placenta." (PMID 34154587, 2021).
colorectal cancer (2 papers, 2020 to 2021). A primary or metastatic malignant neoplasm that affects the colon or rectum. "In a recent article, researchers showed for the first time the in situ expression of SIGLEC6 by mast cell (MC) in human colorectal cancer (CRC) tissues." (PMID 33796453, 2021).
COVID-19 (2 papers, 2021 to 2022). A disease caused by infection with severe acute respiratory syndrome coronavirus 2. "SIGLEC6 belongs to the family of sialic acid-binding immunoglobulin-like lectin proteins, out of which SIGLEC1, SIGLEC7 and SIGLEC10 have been implicated to play a role in COVID-19." (PMID 35438176, 2022). "Interestingly, other MC-specific genes, such as SIGLEC6, HDC, KIT, and others were not increased in COVID-19 lung tissue." (PMID 33777047, 2021).
colon cancer (1 paper, 2021). "SIGLEC6 is up-regulated on MC when stimulated with hypoxia or colon cancer cells." (PMID 33796453, 2021).
eosinophilic esophagitis (1 paper, 2022). Eosinophilic esophagitis (EoE) is a chronic, allergic disease of the esophagus characterized clinically by symptoms of esophageal dysfunction (including vomiting, dysphagia, feeding disorders, food impaction and abdominal pain) which persist after treatment with proton pump inhibitors (PPIs). "Employing single-cell RNAseq on biopsy samples from two distinct cohorts of patients with eosinophilic esophagitis (EoE), in which MCs are overrepresented in the tissue, SIGLEC6 transcript was only detected in MCs." (PMID 35406705, 2022).
HELLP syndrome (1 paper, 2023). A life-threatening condition that can potentially complicate pregnancy. "Interestingly, SIGLEC6 appears to be differentially expressed in parallel with other genes implicated in related disorders like the HELLP syndrome that may denote a common pathway in hypertensive diseases of pregnancy." (PMID 38099221, 2023).
mucosa-associated lymphoid tissue lymphoma (1 paper, 2021). "In addition, compared with normal lymphoid cells and some other lymphoid malignancies, SIGLEC6 is highly expressed in mucosa-associated lymphoid tissue lymphoma." (PMID 33796453, 2021).
Obesity (1 paper, 2020). Accumulation of substantial excess body fat. "An additional gene of interest in this region is SIGLEC6 that binds the obesity-associated leptin molecule." (PMID 32728162, 2020).
urticaria (1 paper, 2023). A vascular reaction of the skin characterized by erythema and wheal formation due to localized increase of vascular permeability. "We found significant trans-pQTL associations of the GCSAML urticaria-associated variant with plasma levels of five proteins encoded by TPSAB1, TPSB2, KIT, SELP, and SIGLEC6 (P-values < 1.0 × 10−7)." (PMID 37430141, 2023).
tumor (8 papers, 2015 to 2024). "The interaction between sialylated glycans and SIGLEC6 can modulate immune cell function during tumorigenesis, resulting in an immunosuppressive tumor microenvironment." (PMID 37974107, 2023). "The 20 most highly and lowly expressed genes were presented, and we noted that the SIGLEC family genes SIGLEC15 and SIGLEC6 were in the 20 most highly expressed genes in tumor samples." (PMID 36159823, 2022). "A number of fast evolving, placental genes show tumorigenic or tumor suppression activity (ADAM12, ADAMTS18, CAPN6, EGFL6, HTRA4, LIN28B) and others are involved in disorders associated with epithelial and connective tissues (FBN2) or have immune functions (IL1RL1, PRG2, SIGLEC6)." (PMID 26641094, 2015). "As is shown in the multi-colour immunofluorescence staining analysis of 135 GC tissues, ~90% of tissues show that NECTIN2, CEACAM1, HMGB1, SIGLEC6 and CD15 were expressed in tumour cells, and CD44 was expressed in tumour cells in about 70% of tissues." (PMID 33311518, 2020).
SIGLEC6 also shares sentences with these, for which no sentence is quoted: cancer (5 papers); acute myeloid leukemia (1); atherosclerosis (1); gastric cancer (1); Immunodeficiency (1); leukemia (1); pancreatic adenocarcinoma (1); pregnancy disorder (1).